CCDC194 (coiled-coil domain containing 194)
Gene: Protein-coding gene on chromosome 19 (17,387,196 to 17,394,196, reverse strand). Ensembl gene ENSG00000269720.
Genetic constraint (gnomAD): Loss-of-function variants: 5 observed, 4.89 expected, observed/expected ratio (o/e) 1.02, 90% interval 0.52 to 1.82. That is too few expected variants to judge how well the gene tolerates losing a copy. Missense variants: 49 observed, 41.42 expected, observed/expected ratio (o/e) 1.18, 90% interval 0.94 to 1.5. Synonymous variants: 13 observed, 14.95 expected, observed/expected ratio (o/e) 0.87, 90% interval 0.56 to 1.38.
Homologues: Orthologues: chimpanzee CCDC194 (98% identical), macaque CCDC194 (95% identical), dog CCDC194 (82% identical), pig CCDC194 (79% identical), mouse Ccdc194 (67% identical), rat Ccdc194 (66% identical), guinea pig CCDC194 (52% identical).